PLA2G6 (phospholipase A2 group VI)
Diseases named in the same sentence as PLA2G6 in open-access papers (continued):
Sharing a sentence is not in itself a finding about the gene and the disease.
Parkinsonism (continued). "Interestingly variants in PLA2G6 associated with both melanoma and naevi in recent GWAS, have very recently been linked to Parkinson’s disease and the incidence of melanoma is greater in Parkinson cases than in controls." (PMID 23796690, 2013). "Subsequent studies identified PLA2G6 mutations in patients with dystonia-parkinsonism." (PMID 20886109, 2010). "PLA2G6 was first associated to PD in 2009 by mutational analysis in three individuals from two unrelated families with adult-onset dystonia-parkinsonism (PARK14), and, surprisingly, none of the affected patients showed brain iron accumulation." (PMID 34299248, 2021). "We identified heterozygous variants in genes associated with recessive PD and parkinsonism, including one in DNAJC6, six in VPS13C, two in SYNJ1, three in PLA2G6 and one in FBXO7 in early-onset cases." (PMID 39867380, 2025). "This systematic review explores the genotype–phenotype correlations of GLB1, SLC6A3, SLC30A10, PLA2G6, and SLC39A14—recently classified as DYT SLC39A14 and historically linked to dystonia-parkinsonism." (PMID 40362326, 2025). "This review on GLB1, SLC6A3, SLC30A10, SLC39A14, and PLA2G6 is the third MDSGene review series on DYT/PARK genes, following previous articles on DRD genes and X-linked dystonia-parkinsonism." (PMID 40362326, 2025). "Astrocytes are known to be become reactive in Parkinson’s disease that includes neuroinflammation, and several genes implicated in Parkinson’s are expressed in both astrocytes and neurons (e.g., PARK7, SNCA, PLA2G6, ATP13A2, LRRK2, PINK1, and PARK2)." (PMID 40972575, 2025). "The initial diagnosis for the boy was early-onset parkinsonism, classified as Hoehn-Yahr grade 5.Genomic sequencing of the patient indicated that he had compound heterozygous variations in the PLA2G6 gene: c.1454G>A (p.Gly485Glu) and c.991G>T (p.Asp331Tyr)." (PMID 38699051, 2024). "PLA2G6-associated neurodegeneration (PLAN) comprises three diseases with overlapping features: infantile neuroaxonal dystrophy (INAD), atypical neuroaxonal dystrophy (atypical NAD), and PLA2G6-related dystonia-parkinsonism." (PMID 39425167, 2024). "Disorders associated with pathogenic variants in the PLA2G6 gene are: INAD, atypical NAD (aNAD) and PLA2G6-related dystonia-parkinsonism, also called Parkinson disease 14 (PARK14)." (PMID 39425167, 2024). "Homozygous pathogenic PLA2G6 variants are the causes of Infantile neuroaxonal dystrophy 1 (OMIM #256600), Neurodegeneration with brain iron accumulation 2B (OMIM #610217), and Parkinson disease 14 (OMIM #612953)." (PMID 38622594, 2024). "Apart from the unusually late age of onset, the presentation of the disease was consistent with the phenotypes of previous patients carrying p.Val691del or p.Thr319Met, and also with what is known about adult‐onset PLA2G6‐related parkinsonism in general." (PMID 37139542, 2023). "PLA2G6-related parkinsonism shows a fairly distinct phenotype of young onset parkinsonism/dystonia, gait/balance, and/or psychiatric/cognitive symptoms." (PMID 38028602, 2023). "The most frequent phenotypes were INAD, PLA2G6-related parkinsonism, and ANAD, accounting for 44%, 41.33%, and 5.33% of cases (total 75), respectively." (PMID 35624904, 2022). "A search of publications between January 2009 and November 2019 was carried out in the PubMed and EMBASE international databases using the following terms: dystonia OR Parkinson OR dystonia-parkinsonism OR parkinsonism AND PLA2G6 OR NBIA2B OR PLAN OR PARK-14." (PMID 35329915, 2022). "PLA2G6-related dystonia-parkinsonism, on the other hand, typically has an onset of psychiatric symptoms, cognitive decline, pyramidal, extrapyramidal, and cerebellar features in young adulthood." (PMID 36247768, 2022). "Among the 34 adult onset PLA2G6-related parkinsonism patients, 76% (26/34) had pyramidal signs, 38% (13/34) displayed cerebellar atrophy, and 26% (9/34) iron deposition." (PMID 35911906, 2022).
Parkinsonism (continued). "The clinical characteristics of PLA2G6-related parkinsonism were different between the Chinese and European populations." (PMID 35624904, 2022). "Up to now, there are only 21 ANAD and 86 PLA2G6-related parkinsonism patients reported in literature." (PMID 35911906, 2022). "In recent years, considering common features of DP, AREP, and sporadic early onset parkinsonism (EOP), scholars have proposed the concept of phenotypic continuum to describe PLA2G6-related parkinsonism, the most common phenotype in late-onset PLAN." (PMID 35911906, 2022). "The frequencies of psychiatric features, cognitive decline, and myoclonus in Chinese patients with PLA2G6-related parkinsonism were significantly different from those in European patients." (PMID 35624904, 2022). "Overall, 22 patients in the Chinese population contributed to the phenogenotypic description of PLA2G6-related parkinsonism." (PMID 35624904, 2022). "Based on this study, levodopa can be effective in PLA2G6-related parkinsonism patients for some periods of time, but further clinical observations are required to determine its long-term efficacy." (PMID 35624904, 2022). "PLA2G6-related dystonia-parkinsonism has a variable age of onset, but most individuals present in early adulthood with gait disturbance or neuropsychiatric changes." (PMID 35207493, 2022). "Infantile neuroaxonal dystrophy (INAD) is a rare paediatric neurodegenerative condition caused by mutations in the PLA2G6 gene, which is also the causative gene for PARK14-linked young adult-onset dystonia parkinsonism." (PMID 35970890, 2022). "Based on the age of onset and clinical manifestations, PLAN can be divided into three major subtypes: infantile neuroaxonal dystrophy (INAD), atypical neuroaxonal dystrophy (ANAD) and PLA2G6-related parkinsonism." (PMID 35624904, 2022). "Summary of demographic and clinical findings of reported 34 adult onset PLA2G6-related parkinsonism patients." (PMID 35911906, 2022). "PLA2G6-dystonia-parkinsonism (PLAN-DP) is characterized by levodopa responsive parkinsonism and dystonia." (PMID 35329915, 2022). "In 2019, Chiu and colleagues generated a KI mouse model harboring the homozygous human PLA2G6 D331Y (GAC→TAC) mutation, which associates with Parkinsonism in humans (Pla2g6D331Y/D331Y)." (PMID 34356877, 2021). "The different PLAN types depend on the age of onset and severity of symptoms and can be divided into classic infantile neuroaxonal dystrophy (INAD), atypical neuroaxonal dystrophy (NAD) and PLA2G6-related dystonia-parkinsonism." (PMID 34769423, 2021). "Research has also shown that disruption of retromer function either by ablation of Parkinsonism related PLA2G6 and VPS35, or by overexpression of alpha-synuclein, leads to ceramide accumulation, lysosomal and mitochondrial stress, and neurodegeneration." (PMID 34514546, 2021). "The slow progression, rigidity, bradykinesis, and the prominent psychiatric symptoms indicate PLA2G6-related dystonia-parkinsonism." (PMID 34168672, 2021). "Genes whose mutations have been associated with parkinsonism include autosomal dominantly (α-synuclein, LRRK2, VPS35, EIF4G1) as well as recessively (PARK2, PINK1, DJ-1, SYNJ1, and PLA2G6) inherited mutations." (PMID 34299248, 2021). "Similar results were observed in fibroblasts derived from patients suffering from INAD and PLA2G6-related dystonia-parkinsonism." (PMID 34769423, 2021). "Loci associated with rare monogenic forms of Parkinson’s disease, or more complex disorders with a prominent component of parkinsonism, also encode proteins involved in vesicle trafficking: VPS35, ATP13A2, PLA2G6, DNAJC6, SYNJ1, and VPS13C." (PMID 33556113, 2021). "A link has also been uncovered between Parkinson's disease and PLA2G6 (PARK14), the gene encoding phospholipase A2 group VI (PLA2G6)." (PMID 34335440, 2021).
Parkinsonism (continued). "Recessive mutations cause three different but overlapping phenotypes: classic infantile neuroaxonal dystrophy, atypical neuroaxonal dystrophy, and PLA2G6-related dystonia-Parkinsonism." (PMID 33426505, 2020). "Moreover, both α-synuclein and the phospholipase PLA2G6, the latter implicated in neurodegeneration with brain iron accumulation and early-onset dystonia parkinsonism, have been associated with changes in lysosomal ceramide levels, though the exact mechanisms are still unknown." (PMID 32172343, 2020). "Mutations of PLA2G6 gene are responsible for PARK14, an autosomal recessive L-DOPA responsive dystonia/parkinsonism with early/adult onset." (PMID 30042723, 2018). "By contrast, PLA2G6-related dystonia-parkinsonism is manifested in late adolescence/early adulthood with marked cognitive decline, pyramidal tract signs, and eye movement abnormalities." (PMID 28821231, 2017). "PLAN is characterized by three phenotypes, including infantile neuroaxonal dystrophy (INAD), atypical neuroaxonal dystrophy (NAD), and PLA2G6-related dystonia-parkinsonism." (PMID 28821231, 2017). "Homozygous mutations in PLA2G6 are associated with a spectrum of neurodegenerative phenotypes: INAD, atypical neuroaxonal dystrophy, and PLA2G6-related dystonia and Parkinsonism." (PMID 28634552, 2017). "Mutations in the gene encoding phospholipase A2 group VI calcium‐independent (PLA2G6, also known as iPLA2β or iPLA2‐VIA) have been associated with two diseases: phospholipase associated neurodegeneration (PLAN, NBIA type 2) and dystonia‐parkinsonism." (PMID 25870938, 2016). "Prominent brain iron accumulation eventually with cerebellar atrophy can be the main neuroradiological sign in atypical INAD whereas non-specific changes such as cerebral atrophy are reported for individuals with PLA2G6-related dystonia-parkinsonism." (PMID 24847269, 2014). "PLA2G6 gene is a candidate gene for one form of monogenic Parkinson disease and has been assigned as ParK14 locus." (PMID 25657764, 2014). "We particularly highlight the role of PLA2G6-related neurodegeneration in patients with juvenile and adult-onset disease complicated by dystonia and parkinsonism with normal MRI imaging." (PMID 20619503, 2012). "Few studies in Africa reported PLA2G6‐associated disorders and none with parkinsonism of late adult onset." (PMID 37139542, 2023). "Four neurological disorders with infantile, juvenile, or early adult‐onset are associated with PLA2G6 genetic alterations, namely infantile neuroaxonal dystrophy (INAD), atypical neuroaxonal dystrophy (ANAD), dystonia‐parkinsonism (DP), and autosomal recessive early‐onset parkinsonism (AREP)." (PMID 37139542, 2023). "Interestingly, both PLA2G6 and GBA genes are associated with PD/parkinsonism and the fly models share many similar phenotypes yet the data clearly show that the cellular origin of the phenotypes is quite different." (PMID 36875645, 2023). "Moreover, variants in PLA2G6 also cause atypical NAD (aNAD) (OMIM # 610217) and PLA2G6-related dystonia-parkinsonism, also called Parkinson disease 14 (PARK14) (OMIM #612953)." (PMID 36645408, 2023). "In addition to the nervous system, case 2 developed special facial features, skeletal deformities, microcephaly, and systemic dermatitis, which have been rarely reported in PLA2G6-related parkinsonism patients to date." (PMID 35624904, 2022). "Neither of the mutations had been reported in PLA2G6-related parkinsonism, making it hard to distinguish AREP from other early onset genetic parkinsonism only by these clinical features." (PMID 35911906, 2022). "PLA2G6-related young-onset dystonia–parkinsonism is listed as PARK14." (PMID 36033628, 2022). "PLA2G6-related parkinsonism includes autosomal recessive early-onset parkinsonism (AREP, known as PARK14) and adult-onset dystonia-parkinsonism (DP), and these patients may present with parkinsonism, dystonia, cognitive regression, and gait instability." (PMID 35624904, 2022).
Parkinsonism (continued). "Multicenter studies with large samples may help to clearly identify the characteristics of PLA2G6-related parkinsonism in the population." (PMID 35624904, 2022). "Mutations to CaI-PLA2’s encoding gene, PLA2G6, are linked to Parkinsonism and PD." (PMID 36358947, 2022). "Interestingly, mutations in PLA2g6 are associated with familial Parkinson’s disease and they found that knockout of PLA2g6 in mice resulted in Parkinson’s disease like symptoms." (PMID 35821821, 2022). "PLA2G6 mutations (e.g., D331Y, R365Q, R714Q, R747W) were also found to be associated with familial forms of PD (PARK14) characterized by AR inheritance and early-onset dystonia-Parkinsonism." (PMID 34356877, 2021). "Another study reported PLA2G6 (PARK14), an important paralog of ANKRD22, as a parkinsonism-associated gene, which its mutation influences the onset of neurodegenerative disorders, including early-onset parkinsonism." (PMID 34574038, 2021). "In particular, the roles of iPLA2β in neuronal function have received extensive attention, since numerous mutations of the PLA2G6 gene have been discovered in patients with neurodegenerative disorders such as infantile neuroaxonal dystrophy (INAD) and Parkinson’s disease." (PMID 33086624, 2020). "Another gene related with Parkinsonism is the phospholipase A2 group VI gene (PLA2G6)." (PMID 31331075, 2019). "Currently, some researchers believe that the PLA2G6 mutation is not a major risk factor for Parkinson's disease in Asian populations." (PMID 30619057, 2018). "In humans, mutations in PLA2G6 lead to a spectrum of hereditary disorders classified as neurodegeneration with brain iron accumulation (NBIA), infantile neuroaxonal dystrophy (INAD), adult dystonia-parkinsonism, and Parkinson disease." (PMID 27630583, 2016). "Tan and colleagues discuss a patient with dystonia-parkinsonism with onset at age 69 who had a PLA2G6 mutation but did not have evidence of iron deposition on CT scan." (PMID 23316402, 2012). "Recently families with adult onset dystonia-parkinsonism were found to have mutations in the PLA2G6 gene but absent iron deposition on magnetic resonance imaging (MRI)." (PMID 20619503, 2012). "The finding of Lewy body pathology in PLA2G6 bridges a link with other neurodegenerative diseases like Parkinson's disease and dementia with Lewy bodies and may shed light on shared pathological pathways." (PMID 20619503, 2012). "Mutations in the PLA2G6 gene have been identified in autosomal recessive neurodegenerative diseases classified as infantile neuroaxonal dystrophy (INAD), neurodegeneration with brain iron accumulation (NBIA), and dystonia-parkinsonism." (PMID 20886109, 2010). "In addition to pathogenic mutations in well-established PD-related genes (LRRK2, PRKN, PINK1, SNCA, PLA2G6 and GBA1), we identified pathogenic mutations in genes that have been reported to present as levodopa-responsive parkinsonism but typically present with alternative or atypical phenotypes." (PMID 39420034, 2024). "Moreover, atypical or complex parkinsonism may be due to mutations in genes such as ATP13A2, DCTN1, DNAJC6, FBXO7, PLA2G6, and SYNJ1." (PMID 35328025, 2022). "PLA2G6-associated neurodegeneration (NBIA/DYT/PARK-PLA2G6) comprises a continuum of three phenotypes with overlapping clinical and radiologic features: infantile neuroaxonal dystrophy (INAD), atypical neuroaxonal dystrophy (atypical NAD), and PLA2G6 -related dystonia-parkinsonism." (PMID 35207493, 2022). "Therefore, potential and novel biomarkers are required for PLA2G6-mediated parkinsonism." (PMID 36033628, 2022). "AR mutations in the phospholipase A2 group (PLA2G6) are causative of the PLAN phenotypic spectrum, including classic infantile neuronal dystrophy (INAD), atypical neuronal dystrophy (NAD) with childhood-onset, and an adult onset dystonia-parkinsonism form named PARK14." (PMID 33092153, 2020).
Parkinsonism (continued). "Since many of the pathological hallmarks of PLA2G6 disorders including the accumulation of brain iron, are also observed in Alzheimer’s and Parkinsons disease, any genes or compounds that suppress these phenotypes may also have therapeutic effects in a broad spectrum of neurodegenerative diseases." (PMID 29440694, 2018). "In contrast, dystonia-parkinsonism mutations do not appear to directly impair catalytic function, but may modify substrate preferences or regulatory mechanisms for PLA2G6." (PMID 20886109, 2010). "Since PLA2G6 has also been observed to hydrolyze palmitoyl coenzyme A (CoA) in vitro, we examined PLA2G6 catalytic activity using radiolabeled palmitoyl CoA, and observed that the dystonia-parkinsonism mutations also do not impair PLA2G6 thioesterase activity." (PMID 20886109, 2010). "Our analysis showed dystonia-parkinsonism predominates in SLC6A3 and PLA2G6, while GLB1, SLC30A10, and SLC39A1 show predominantly dystonic phenotypes with a low frequency of parkinsonism." (PMID 40362326, 2025). "Literature review of PLA2G6-AREP patients showed that, in addition to early-onset parkinsonism, pyramidal signs (76%), cerebellar atrophy (38%), and iron deposition of globus pallidus (26%) are also common in these patients." (PMID 35911906, 2022). "Finally, PLA2G6, aliase PARK14, codes for a phospholipase A2, group 6 which hydrolases membrane phospholipids and may contribute, via lipid peroxidation, to CNS injury and disorders, such as Parkinson's disease." (PMID 25525598, 2014). "This study indicated that defects in PLA2g6 mediated SOCE, possibly via decreased Orai1 activity, could be a novel mechanism contributing to Parkinson’s disease." (PMID 35821821, 2022). "This suggests that phospholipase activity is not the only important aspect in iPLA2-VIA mediated cytoprotection, possibly explaining the observation that mutations associated with PLA2G6-associated dystonia-parkinsonism do not disrupt catalytic activity." (PMID 34506510, 2021). "With the exception of SLC6A3 and PLA2G6, which primarily manifest with dystonia and parkinsonism as key features, we found that GLB1, SLC30A10, and SLC39A14 predominantly exhibit a dystonic phenotype, sometimes accompanied by other movement disorders, such as parkinsonism or ataxia." (PMID 40362326, 2025). "Other genes such as APT13A2, PLA2G6, FBXO7, and the more recently identified DNAJC6, SYNJ1, and VPSC13 are usually related to younger onset Parkinsonism, complicated by atypical motor and non-motor phenotypes." (PMID 34630269, 2021).